Y_RNA (Y RNA )
Gene: Miscellaneous RNA gene on chromosome 3 (157,153,548 to 157,153,640, forward strand). Ensembl gene ENSG00000201778.
Homologues: Orthologues: chimpanzee Y_RNA (99% identical). Paralogues in human: RNY4P10 (91% identical), RNY4 (88% identical), RNY4P13 (86% identical), RNY4P7 (86% identical), Y_RNA (86% identical), RNY4P14 (85% identical), RNY4P6 (85% identical), RNY4P9 (85% identical), Y_RNA (85% identical), RNY4P19 (84% identical), RNY4P25 (84% identical), RNY4P27 (84% identical), and 89 more.